AMH (anti-Mullerian hormone)
Diseases named in the same sentence as AMH in open-access papers (continued):
Sharing a sentence is not in itself a finding about the gene and the disease.
Obesity (continued). "Contradictory results in AMH levels have also been reported following lifestyle interventions combined either with sibutramine or orlistat in women with obesity." (PMID 38559698, 2024). "In another study, the analysis of AMH values was performed in 53 patients with obesity before and 3 and 6 months after sleeve gastrectomy." (PMID 34878586, 2022). "Nevertheless, among women with obesity and anovulation, it is common to find more small antral follicles that secrete AMH." (PMID 36114550, 2022). "A multiple linear regression analysis was used to identify the relationship among AMH, 25-OH-D, obesity, MetS, sexual hormones, sociodemographic and lifestyle factors." (PMID 35835777, 2022). "In this narrative review, we evaluated the impact of obesity on AMH levels in healthy, regularly cycling reproductive-age women (18–48 years)." (PMID 34300357, 2021). "Thirteen studies (n = 1214 women; (811, non-obese (body mass index; BMI < 30 kg/m2); 403, obese (BMI > 30 kg/m2))) were included, of which five reported decreased AMH levels with obesity, whereas eight showed comparable AMH levels between groups." (PMID 34300357, 2021). "Our current demographic necessitates further consideration of the impact of obesity on AMH production in healthy women of reproductive age." (PMID 34300357, 2021). "However, the wide use of AMH is still limited because of analytic diversity, missing or contradictory age- and ethnic-specific thresholds, as well as additional factors modulating AMH levels, including obesity, hormonal drug use, and ovarian surgery." (PMID 41515619, 2026). "We have correlated them with BMI values to determine whether overweight/obesity influence AMH in these patients." (PMID 40283506, 2025). "Because obesity is, as emphasized earlier, often associated with PCOS, it becomes even more crucial to determine its correlation with a potential diagnostic factor of PCOS, such as AMH levels." (PMID 40283506, 2025). "Notably, higher BMI, characteristic of obesity, is strongly associated with PCOS but inversely associated with serum AMH." (PMID 40108611, 2025). "There are reports of low AMH levels in men with obesity, diabetes, and metabolic syndrome." (PMID 39032500, 2024). "Ultimately, though, it remains uncertain at this point how obesity may adversely affect AMH levels and potentially ovarian reserve in otherwise healthy women with regular menstrual cycles, thus necessitating the performance of large-scale prospective studies." (PMID 39683543, 2024). "The diagnostic cut-off values of AMH in individuals with and without obesity are 5.63 and 5.06, respectively." (PMID 38600539, 2024). "More studies have not shown an association between obesity and AMH in premenopausal female subjects or healthy female patients." (PMID 38737557, 2024). "Specifically, obesity was found to be associated with lower AMH levels in women with or without PCOS." (PMID 36766605, 2023). "Previous studies have shown a negative association between AMH and BMI in women with overweight and obesity, which was not seen in this study." (PMID 36309748, 2022). "There is also evidence of reduced or normalized AMH-levels after diet-induced weight loss in women with PCOS and overweight or obesity, whereas other studies show improved reproductive function without concomitant changes in AMH- levels." (PMID 36309748, 2022). "Low AMH reflects decreased follicular function, which could be a result of the inflammatory markers in the ovaries, secreted in cases of obesity." (PMID 36114550, 2022). "This conclusion is prudent considering that the biological basis for an impact of obesity on AMH production is unknown." (PMID 34300357, 2021). "The mechanisms through which obesity may adversely affect AMH production are unknown, but it has also been shown that with increasing adiposity, AMH production per antral follicle is reduced." (PMID 34300357, 2021).
Obesity (continued). "Obesity, IR, HA and gonadotrophin imbalance probably have an impact on higher anti-Müllerian hormone (AMH) levels in women with PCOS compared to healthy women, which is connected with an increased number of antral follicles and higher production of AMH per antral follicle." (PMID 34068234, 2021). "Obesity has been posited to alter Anti-Müllerian hormone (AMH) production." (PMID 34300357, 2021). "Inclusion of women with higher obesity classes (Class 3 versus Class 1) may have been a factor in studies reporting lower AMH levels." (PMID 34300357, 2021). "Another possibility includes an impact of obesity on AMH catabolism and excretion." (PMID 34300357, 2021). "The unbalanced representation of obesity in this cohort alongside any confounding effects of OCP use may have impacted the ability to detect an impact of obesity on AMH levels." (PMID 34300357, 2021). "In the present work, we aimed to provide an updated review of whether obesity per se affects AMH production in healthy, potentially fertile women." (PMID 34300357, 2021). "Few studies have prospectively evaluated the relationship between obesity and AMH production, and more mechanistic studies are needed to better understand how obesity and/or alterations in metabolic status could regulate AMH." (PMID 34300357, 2021). "Some women with obesity have regular cycles, yet their reproductive hormone profile suggests some level of ovarian dysfunction that could manifest as disordered AMH production compared to their lean counterparts." (PMID 34300357, 2021). "Given that previous evidence supports that severe obesity may lower AMH levels and possibly ovarian reserve, it is critical to address this knowledge gap." (PMID 34300357, 2021). "More indirect in nature is the notion that lower AMH levels in women with obesity may result from a hemodilution effect of increasing body size." (PMID 34300357, 2021). "Anti-Mullerian hormone (AMH), a glycoprotein primarily produced by the granulosa cells of primary and early-stage antral follicles, is a marker whose association with obesity is controversial —albeit a single meta-analysis suggests a negative association of AMH with BMI." (PMID 34300357, 2021). "While this posited mechanism may explain a reduced ovarian follicle pool and AMH levels, it seems less likely based on existing data of a later time to ovarian senescence in women with obesity." (PMID 34300357, 2021). "Ultimately, the degree to which obesity may negatively impact AMH levels, and possibly ovarian reserve, in otherwise healthy women with regular menstrual cycles should be deemed uncertain at this time." (PMID 34300357, 2021). "Also, our data indicated that obesity along with elevated levels of AMH and testosterone levels in the ovarian microenvironment are the most likely factors that cause the poor ovarian response in patients with PCOS." (PMID 31980027, 2020). "Secondly, as testosterone directly inhibits production of AMH, any obesity related reduction in testosterone production is likely to result in a reflex increase in AMH production, potentially masking any obesity related impairment in Sertoli cell function assessed by serum AMH." (PMID 28286655, 2017). "At the end of the study, 76% of patients switched from obesity to overweight, 96% of participants had normalization HOMA-IR, serum AMH levels significantly decreased, and progesterone and SHBG significantly increased after VLCKD." (PMID 39328462, 2024). "Specifically, OC, MET and CC lead to decreased AMH level, DHEA and VD lead to increased AMH level, and GnRH-a leads to dynamic variation, which is correlated with PCOS, obesity, age, and duration of medication." (PMID 35698127, 2022). "In addition, it has been suggestedthat obesity may affect the catabolism of AMH." (PMID 33687164, 2021).
Obesity (continued). "Regarding the importance ofAMH, the prevalence of obesity and related dysfunctionof adiponectin in PCOS, the aim of present study was todetermine the correlation between AMH, adiponectin andoxidative stress markers in PCOS patients." (PMID 32112632, 2020). "A negative correlation between obesity and AMH has also been reported in which lower AMH levels were attributed to other physiological processes rather than specifically the ovarian reserve." (PMID 38625059, 2024). "Contrary to the literature stating that AMH levels are inversed correlated to BMI, in our study women with obesity had high AMH levels before BS, regardless of PCOS status." (PMID 38559698, 2024). "Discrepancy in the statistical significance in the changes of AMH and AFC throughout the study period may be related to the greater intracycle and inter-cycle variation of the AFC in women with obesity or to the limited sample size." (PMID 38559698, 2024). "According to different clinical manifestations, PCOS exists in patients with and without obesity, and the AMH level in patients with and without obesity is also different." (PMID 38600539, 2024). "Since the source of AMH is preantral and small antral follicles, which are not impacted by obesity, it is reasonable that obesity has no impact on AMH levels." (PMID 38370492, 2023). "The aim of this study was to investigate circulating AMH levels in a population of women with severe obesity (BMI ≥ 35 kg/m2) with and without PCOS, as diagnosed by the NIH-criteria." (PMID 36309748, 2022). "Taken together, in women with severe obesity, circulating AMH is higher in women with PCOS and positively correlated with androgen levels, but AMH did not decrease with significant weight loss in women with or without PCOS." (PMID 36309748, 2022). "Here we demonstrate that women with PCOS and severe obesity have higher circulating AMH levels than women with similar BMI without PCOS." (PMID 36309748, 2022). "In a prospective cohort-study, were 246 women with severe obesity were screened for PCOS diagnosis with the NIH-criteria, circulating AMH and anthropometry were measured at baseline and after a 12-month weight loss intervention with very low-energy diet (VLED)." (PMID 36309748, 2022). "Overall, the data do not support a consistent impact of obesity on AMH levels in women with regular menstrual cycles." (PMID 34300357, 2021). "Our evaluation is consistent with most studies showing comparable AMH levels between obese and non-obese groups of reproductive-aged women with regular menstrual cycles, wherein women with obesity primarily presented with milder obesity status." (PMID 34300357, 2021). "Collectively, the findings of this review do not corroborate a consistent negative impact of obesity on AMH." (PMID 34300357, 2021). "This aligns with a recent narrative review of 13 studies on AMH in women, which could not demonstrate any clear impact of obesity on AMH levels." (PMID 38737557, 2024). "Moreover, they decreased after BS in both PCOS and non-PCOS subgroups, suggesting that high AMH levels are probably a common feature of women with obesity, possibly related to metabolic or hormonal alterations specific to the obesity condition." (PMID 38559698, 2024). "Finally, a one-year weight reduction program does not affect circulating AMH levels despite significant weight loss neither in women with PCOS, nor without PCOS and severe obesity." (PMID 36309748, 2022). "In ROC analyses, circulating free testosterone had higher sensitivity and specificity than AMH, thus AMH could not be used to discriminate between women with severe obesity with and without the syndrome with enough precision." (PMID 36309748, 2022). "To address the current knowledge gap, we conducted a review to provide an up-to-date account of AMH levels in obese and non-obese women with regular menstrual cycles with the goal of establishing the degree to which obesity impacts AMH production in healthy, potentially fertile women." (PMID 34300357, 2021).
Obesity (continued). "Overall, these results suggest that obesity may have a negative impact on AMH across the obesity spectrum with a dose effect that is not linear." (PMID 34300357, 2021). "Consequently, women over 35 years, with low AMH < 10 pmol/L, or obesity, were not included in the present study." (PMID 31616381, 2019). "Studies reporting AMH levels in otherwise healthy women are primarily limited by small sample size, cross-sectional design, and lack of representation across the entire adiposity spectrum—with an existing emphasis on lower obesity classes and absence of women who are overweight." (PMID 34300357, 2021). "Ultimately, the notion of a negative impact of obesity on AMH in healthy women with regular menstrual cycles may be deemed uncertain at this time—or at best limited to women with severe obesity, warranting further investigations to address the limitations of the current evidence." (PMID 34300357, 2021). "Our study revealed that AMH exhibited a higher predictive value for PCOS in both individuals with and without obesity." (PMID 38600539, 2024). "Women with severe obesity and PCOS have elevated levels of circulating AMH compared to women without the syndrome." (PMID 36309748, 2022). "Our present study has clarified the correlation of AMH and metabolism and hormones in individuals with PCOS with and without obesity to a certain content, but more in-depth and large-sample studies are required to further explore the exact regulatory mechanism." (PMID 38600539, 2024). "On the other hand, women with PCOS with low serum AMH levels may not have ovarian cysts; their primary pathology may not reside in the ovaries, but they may develop PCOS because of obesity and insulin resistance, which may be similar to the metabolic subtype." (PMID 36766605, 2023). "Next, we performed ROC-analyses, and show that circulating AMH could not discriminate women with PCOS and severe obesity from non-PCOS women with severe obesity." (PMID 36309748, 2022). "However, to our knowledge, there is no study to date investigating AMH-levels in women with PCOS and severe obesity, compared to controls, and the effect of diet-induced weight loss on circulating AMH." (PMID 36309748, 2022). "The authors showed lower AMH levels in obese women based on a pooled analysis involving 211 obese and 233 non-obese, fertile non-PCOS women (weighted mean differences, −0.94, 95% CI −1.14, −0.73 ng/mL) and a negative relationship between AMH and obesity." (PMID 34300357, 2021). "Moreover, the study has shown that women with PCOS exhibited higher levels of AMH, elevated LH: FSH ratio, and reduced FF progesterone levels, confirming these as signatures of PCOS regardless of BMI, and obesity mainly exacerbates metabolic dysfunction rather than modulating reproductive outcomes." (PMID 41149632, 2025).
breast carcinoma (32 papers, 2013 to 2026). "The impact of a germline BRCA1/2 pathogenic variant (gBRCApv) on baseline or late post-treatment AMH concentrations in breast cancer patients has been extensively studied, yielding mixed conclusions." (PMID 40220108, 2025). "Elevated serum levels of AMH have been associated with increased risk and adverse prognosis in breast cancer." (PMID 38911383, 2024). "In a prospective longitudinal analysis in women with breast cancer, we found that pre‐ and post‐chemo AMH and BRCA pathogenic variant status are predictors of post‐chemotherapy amenorrhea risk." (PMID 37698031, 2023). "In Elaissen and colleagues study, control groups were selected without considering menopausal status, and they allowed postmenopausal women among controls; this caused a higher estimation of the association between breast cancer and AMH." (PMID 33718762, 2021). "The present study result shows that the low level of AMH in young patients is associated with breast cancer, which has also been confirmed by other studies." (PMID 33718762, 2021). "Further, two recent prospective studies observed a strong positive association between increasing categories of AMH and breast cancer." (PMID 33718762, 2021). "We found a positive association between lower and higher AMH levels and breast cancer before anticancer treatment." (PMID 33718762, 2021). "Because of the inconsistent reported results about the association between AMH level and breast cancer, our aim in the present study was to measure the level of AMH in young Iranian breast cancer patients and compare it with healthy controls." (PMID 33718762, 2021). "A recent study showed that breast cancer patients with BRCA mutation have significantly lower serum AMH levels and recommended that fertility preservation should be considered more aggressively in these patients." (PMID 33718762, 2021). "A large-scale study that evaluated the AMH level and risk of breast cancer in 10 prospective cohorts reported a positive relationship between breast cancer and AMH level." (PMID 33718762, 2021). "The results of logistic regression analysis considering confounding factors showed the positive association between breast cancer and lower (Odds Ratio [OR] = 5.98, p = 0.02) and higher quartile of AMH level (OR = 4.95, p = 0.01)." (PMID 33718762, 2021). "It was demonstrated that in the T47D estrogen-positive line of breast cancer cells AMH causes selective expression of mRNA IEX-1S splice variant, and IEX-1L variant, which is responsible for the survival of colonies of cells, was absent." (PMID 30884769, 2019). "Studies have suggested that AMH levels might be reduced at the time of diagnosis in some cancer types, including lymphomas and breast cancer patients with BRCA1 mutations." (PMID 38400669, 2024). "This implies that AMH may be closely associated with the occurrence, diagnosis, treatment, and prognosis of breast cancer." (PMID 37410375, 2023). "They suggested that control subjects of their study were not representative of unaffected women in the cohort and stated that the association between AMH and breast cancer could be biased." (PMID 33718762, 2021). "Therefore, for the accurate evaluation of the association between AMH level and breast cancer, BRCA mutation assessment is necessary." (PMID 33718762, 2021). "Additionally, another team also proved that increased levels of circulating anti-Mullerian hormone (AMH) in premenopausal women were associated with elevated risks of breast cancer." (PMID 34307370, 2021). "Since AMH plays a role in regulating folliculogenesis and the interaction between AMH and estradiol is not fully understood, the abnormal AMH level may affect estradiol concentration that will cause breast cancer." (PMID 33718762, 2021).